TNFSF13 (TNF superfamily member 13)
Diseases named in the same sentence as TNFSF13 in open-access papers (continued):
Sharing a sentence is not in itself a finding about the gene and the disease.
cancer (22 papers, 2017 to 2025). A tumor composed of atypical neoplastic, often pleomorphic cells that invade other tissues. "Previous research has clarified that TNFSF13 is closely associated with cancer occurrence and development, and it may be an effective biomarker for predicting the immunotherapy response." (PMID 37848933, 2023). "In our findings, TNFSF13 was positively associated with signature genes for MMR in most cancers." (PMID 34712225, 2021). "Besides, TNFSF13 was highly associated with T cells in pan-cancer samples." (PMID 34712225, 2021). "TNFSF13 was initially reported to be upregulated in cancer cells, including hematologic and solid malignancies." (PMID 38149239, 2023). "Afterwards, four cell clusters including cancer cells (also called neoplastic cells), M2 macrophages, astrocytes, and T cells were annotated and visualized; meanwhile, we showed the TNFSF13 expression in all clusters." (PMID 34712225, 2021). "We further contrasted the expression level of TNFSF13 in each cluster and confirmed TNFSF13 was notably upregulated in M2 macrophages, T cells, and cancer cells." (PMID 34712225, 2021). "LoCHO_FAT also decreased TNFSF13, a proliferation-inducing member of the TNFSF, which is associated with poor prognosis, indicating its potential as a nutritional intervention strategy for cancer." (PMID 38590952, 2024). "In addition, we investigated the prognostic value of TNFSF13 in other cancers according to OS and DDS." (PMID 34712225, 2021). "FAM3B and TNFSF13 also have known implications in cancer and their altered expression may have some role in prostate tumorigenesis." (PMID 28750683, 2017). "For immunomodulators, we found that the KIFscore was positively correlated with ULBP1, MICB, and CD276, while it was negatively correlated with TNFSF13 and TNFRSF14 in the vast majority of cancers." (PMID 37711200, 2023). "Specifically, TNFSF13 and TNFSF14 can increase the effects of immunotherapy by facilitating immune cell mobilization into the cancer." (PMID 35432372, 2022). "Among those we found TNFSF13: FAS and CCL5: CCR5, two pairs of ligands/receptors that are known to play a role in AML and other cancers." (PMID 32399572, 2020). "Also, in most of the cancers, there was a significant correlation between UBE2C gene expression and C10orf54, CXCL12, IL6R, MICB, PVR, THEM173, and TNFSF13." (PMID 38577722, 2024). "In the present review, we will concentrate on the role of a proliferation-inducing ligand (APRIL, TNFSF13), BAFF (TNFSF13B), and their receptors in cancer, the novel biological therapies targeting this system, their role in breast cancer, and their potential use as therapeutic targets." (PMID 32612943, 2020). "We failed to found reports on GZMH and TNFSF13 expression in EVs of cancer cells." (PMID 35838333, 2022). "In addition, the overall correlation between TNFSF13 and TMB, MSI in 32 cancers was remarkable." (PMID 34712225, 2021).
infection (9 papers, 2013 to 2025). The state of being infected such as from the introduction of a foreign agent such as serum, vaccine, antigenic substance or organism. "We validated this using smFISH, confirming that both Tnfsf13 and its cognate receptor Tnfrsf17 (encoding for the B cell maturation antigen, BCMA) are upregulated in microglia and B cells, respectively, upon infection." (PMID 36180478, 2022). "Pattern "MTB" includes 177 genes whose expression levels changed specifically in response to infection with mycobacteria (e.g. NCF2, TNFSF13, CSF1)." (PMID 26586179, 2015). "In fact, there was a decrease in the mRNA levels of innate-immunity related genes from blood mononuclear cells following intramammary infection with M. bovis, such as complement factor D (CFD), ficolin 1 (FCN1), and tumor necrosis factor superfamily member 13 (TNFSF13)." (PMID 38515536, 2024). "The specific genes in the geneset that associated with the greatest odds of reduced risk of infection including SEMA4A, CTSD, CD68, and GAA were all members of this pathway, but not TNFSF13 (APRIL) which was the most protective gene in the NHP studies." (PMID 34533134, 2021). "Of particular interest, the expression of 6 genes (VSIG4, LAMP1, QPCT, C1QB, TNFSF13, and JUN) can be used to distinguish the transcriptomic signature of a dormant infection from an uninfected joint replacement highlighting the potential for these markers in diagnosing a dormant infection." (PMID 39563367, 2024).
blood cancers (1 paper, 2024). "Among the proteins associated with risk of haematological cancers, we identified associations with risk of multiple blood cancers for members of the FC-receptor protein [FCRL1, FCRL2, FCRL3, FCRL5, FCRLB] and TNF receptor families [TNFRSF4, TNFRSF9, TNFRSF13B, TNFRSF13C, TNFSF13B, TNFSF13]." (PMID 38750076, 2024).
immune dysfunction (1 paper, 2025). "The release of IL-17 and TNFSF13 is related to gut flora imbalance and intestinal mucosal immune dysfunction." (PMID 40642002, 2025).
inflammatory myopathies (1 paper, 2025). "Several tumor necrosis factor (TNF) superfamily genes (TNFSF8, LTB, TNFSF12, TNFSF13B, TNFSF14, TNFSF13, EDA) were upregulated, with LTB and EDA reaching higher levels than in other inflammatory myopathies." (PMID 41441888, 2025).
TNFSF13 also shares sentences with these, for which no sentence is quoted: multiple sclerosis (2 papers); Adult onset (1); Alzheimer disease (1); amyotrophic lateral sclerosis (1); asthma (1); atherosclerosis (1); bacterial infections (1); celiac disease (1); cholangiocarcinoma (1); Crohn disease (1); dementia (1); diabetes (1); eczema (1); endometriosis (1); escherichia coli infection (1); gastric cancer (1); Hypertension (1); inflammation (1); Insulin resistance (1); intestinal disease (1); intestinal infections (1); laryngeal carcinoma (1); laryngeal squamous cell carcinoma (1); low grade glioma (1); lung adenocarcinoma (1); lung fibrosis (1); lung squamous cell carcinoma (1); lymphoma (1); mental illness (1); mesothelioma (1).
A further 17 diseases each share a sentence with TNFSF13 in 1 paper.